MARK2P5 (MARK2 pseudogene 5)
Gene: Processed pseudogene on chromosome 5 (15,384,220 to 15,384,853, forward strand). Ensembl gene ENSG00000248834.
Diseases named in the same sentence as MARK2P5 in open-access papers:
MARK2P5 is named in the same sentence as 1 disease in open-access papers, as found by Europe PMC text mining. Sharing a sentence is not in itself a finding about the gene and the disease.
MARK2P5 shares sentences with these, for which no sentence is quoted: Hyperbilirubinemia (1 paper).